IL10 (interleukin 10)
Diseases named in the same sentence as IL10 in open-access papers (continued):
Sharing a sentence is not in itself a finding about the gene and the disease.
Sepsis (continued). "We described sepsis-induced increase in IL-10 production by monocytes and CD4+ T cells but not B cells and CD8+ T lymphocytes." (PMID 33613540, 2020). "Therefore, IL-15 can be used in combination with other immunotherapeutic agents for sepsis treatment, such as antibodies that block PD-1 or CTLA-4, which have been found to diminish IL-10 production and PD-1 expression on CD8+ T cell." (PMID 32197507, 2020). "An increase in neutrophil activity during sepsis could therefore result in an increased MPXI and also an increased production in IL-10." (PMID 32133380, 2020). "An in vivo study involving an LPS-stimulated mouse model of sepsis reported reduced levels of inflammatory mediators (TNF-α, IL-1β, and IL-6) and an elevated level of the anti-inflammatory cytokine IL-10 in septic mice fed with lyophilized powder of wild bitter gourd-supplemented diet." (PMID 33193799, 2020). "While differential regulation of IL-10 production is beyond the scope of the present manuscript, it is clear that the alterations in the profile of cytokines released by blood leukocytes of CAP patients resemble that of sepsis patients." (PMID 32477337, 2020). "In this study, we found that elevations in IL-6, IL-8, IL-10, MCP-1, and PAI-1 serum levels were common features in patients with sepsis, ARDS, or burns and that the serum IL-6 level was positively correlated with the serum levels of other cytokines and of PAI-1 in CRS patients." (PMID 32826331, 2020). "IL-10 is a crucial anti-inflammatory cytokine and immune support factor and also mediates the downregulation of proinflammatory cytokines such as TNF-α and IL-6 at the early stage of sepsis." (PMID 33376482, 2020). "Previous studies have clearly indicated the importance of IL-1β, IL-6, IL-10, and TNF-α in sepsis." (PMID 33324396, 2020). "Compared to those of control mice, mRNA levels of the IL-6, IL-10, and CCL3 in peripheral blood mononuclear cells (PBMCs) of septic mice were significantly increased, all of which are known to be key markers of sepsis severity and mortality." (PMID 33182773, 2020). "Elevated plasma concentrations of IL-10, IFN-γ, IP-10, IL-12p70, IL-6 and CCL2, were strongly associated with confirmed LOS compared to no LOS; consistent with other preterm infant sepsis studies." (PMID 32407417, 2020). "This is further reinforced by the fact that the M1 cytokines, IL1, IL‐6 and TNF are consistently increased in the hippocampus late after sepsis, and IL‐10 has some peaks during sepsis evolution and CCL‐22 is not increased at all." (PMID 31654493, 2020). "However, a meta-analysis showed IL-8 and IL-10 were substantially lower in Covid-19 as compared to conditions like cytokine release syndrome, Acute Respiratory Distress Syndrome (ARDS), and Sepsis." (PMID 33408715, 2020). "IL-10 in MSC-derived EVs has been shown to polarize macrophages from the proinflammatory M1 to the anti-inflammatory M2 type and to attenuate kidney inflammation and bacteria-induced sepsis." (PMID 33330429, 2020). "This was consistent with previous studies where preterm infants with sepsis had significantly increased IL-10 levels compared to those who were non-infected." (PMID 32479514, 2020). "Also, acupuncture therapies were reported as being capable of decreasing secretion of IL-6, high mobility group protein box-1 (HMGB1), TNF-α, IL-10, and interferon-γ (IFN-γ), demonstrating acupuncture at ST36's potential of reducing inflammation in sepsis." (PMID 32215037, 2020). "Consistent with previous studies, elevated cytokine levels were common in the two types of sepsis of our study and there were also differences in the levels of IL-6 and IL-10 between survivors and nonsurvivors of the two sepsis groups." (PMID 33329592, 2020). "IL-2, IL-6, IL-10, and NLR were significant after univariate regression analysis, but they were not independent risk factors for sepsis in our study." (PMID 32802049, 2020).
Sepsis (continued). "Addition of PTX to GENT after 1.5 and 4 h of sepsis duration, on the other hand, reduced the TNF-to-IL-10 ratio in lung tissue and effectively prevented this pro-inflammatory response observed with GENT treatment alone at the later stages of sepsis in our model." (PMID 33072121, 2020). "Thus, in the AOSD group, FGF-2, GM-CSF, IL-17, IL-18, and VEGF form interrelated networks, whereas in the sepsis group, IFN-γ, TNF-α, IL-8, IL-10, and IL-18 form interrelated networks." (PMID 32381117, 2020). "Additionally, sepsis-induced lymphocyte depletion was ameliorated, levels of circulating pro-inflammatory cytokines TNF-α and IL-6 were increased, anti-inflammatory IL-10 levels were decreased and bacterial clearance was enhanced." (PMID 33336293, 2020). "Non-surviving patients affected by severe sepsis exhibit high IL-10 serum levels and low HLA-DR expression on circulating monocytes compared with surviving patients." (PMID 32516170, 2020). "Other biomarkers that can indicate the immune state in sepsis patients include apoptosis markers (Bim, Bid and Bac), caspases, leukocyte markers (HLA-DR, PD-1, FOXP3, CD127) and cytokines (IL-2, IL-6, IL-12, IL-17, IL-22, IL-33, TNF-α, IFN-γ, IL-10 and TGF-β)." (PMID 33336293, 2020). "Stratifying major surgical patients to those who develop sepsis versus those without complications has uncovered that the last had significantly reduced IL-10 levels." (PMID 32276346, 2020). "LPS-induced sepsis is less severe when injection at ZT10 than at ZT12, coinciding with a decrease in pro-inflammatory cytokines TNF-α, IL-6, and CXCL1 at ZT12, and increase in the anti-inflammatory cytokine IL-10." (PMID 31470863, 2019). "Furthermore, we demonstrated the inhibitory effects of LDK378 on the sepsis-induced up-expression of TNF-a and IL-6 and the enhanced effects of LDK378 on IL-10 expression in septic rats." (PMID 30820191, 2019). "Interestingly, only Olv and Omg decreased the sepsis-induced secretion of the inflammatory cytokines, TNF-α, IL-6, and IL-1β and stimulated the secretion of the anti-inflammatory cytokine, IL-10." (PMID 31333903, 2019). "Inteleukin-10 (IL-10) is a key immunoregulatory cytokine that can suppress potentially damaging pro-inflammatory responses, aid injury resolution, and restore tissue function in both ARDS and sepsis." (PMID 31200579, 2019). "However, HDACs activity (e.g., HDAC6 and HDAC11) are off balanced during sepsis, which alters the transcription of pro- and anti-inflammatory genes (e.g., TNF-α and IL-10, respectively) in vitro and in vivo." (PMID 31416265, 2019). "IL-10 is a key immunoregulatory cytokine that can suppress potentially damaging pro-inflammatory responses and which aids the resolution and restoration of homeostasis in both ARDS and sepsis." (PMID 31200579, 2019). "In this study, we observed that Siglecg deficiency protected mice from over-activation of acute inflammatory responses and death in TLR-triggered sepsis by attenuating TLR-triggered pro-inflammatory cytokine production and increasing anti-inflammatory cytokine IL-10 production." (PMID 31781099, 2019). "It has been reported that BM-MSCs activated by lipopolysaccharide (LPS) or tumor necrosis factor-a (TNF-a) reprogram macrophages to increase the production of interleukin-10 (IL-10) by secreting prostaglandin E2 (PGE2) and attenuate sepsis and improve survival in mouse sepsis models." (PMID 31336889, 2019). "A smaller study comparing 16 septic shock patients with 11 shock patients without sepsis supports the predictive value of systemic IL-10 levels in the first days after admission." (PMID 31795299, 2019). "In contrast to other studies on sepsis, the severity of sepsis was considered better indicated by the rise in plasma IL-10 and the HO1 levels rather than the low HPX levels on admission." (PMID 31554244, 2019).
Sepsis (continued). "This concomitant variation in levels of IL-10 and IL-1β was observed before in the experimental model of sepsis, in which the lack of C5 resulted in lower levels of both cytokines." (PMID 31687410, 2019). "A previous study reported that mice receiving an adoptive transfer of M(IFNγ+LPS+IC) produced a high level of IL-10, resulting in decreased disease severity in autoimmune diseases such as experimental autoimmune encephalomyelitis (EAE) and reduced mortality in sepsis." (PMID 31998290, 2019). "Previous studies report an increase in serum concentrations of IL-6 and IL-10 in healthy dogs 3 days after ovariohysterectomy and identified KC-like as being significantly higher in dogs with pyometra and sepsis compared to dogs without sepsis." (PMID 32010716, 2019). "The IL-10 is completely protective in the LPS model of sepsis and the absence of IL-10 leads to more rapid onset of mortality." (PMID 30949497, 2019). "3.5 months after sepsis, IL-10 expressing B cells were still slightly, but no longer significantly, increased in septic mice." (PMID 29466409, 2018). "We analysed Tregs, IL-10 producing B cells, MDSCs and double negative (DN) T cells 1 week, 1 month and 3.5 months after sepsis induction, replicating the post-acute, late and very late time points, respectively." (PMID 29466409, 2018). "While TGFβ was not significantly increased during sepsis, EX-527 significantly decreased TGFβ and IL10 frequency compared to nontreated CLP mice (p = 0.029 and p = 0.035, resp)." (PMID 30069485, 2018). "We analysed the frequencies and numbers of regulatory T cells (Tregs), double negative T cells, IL-10 producing B cells and myeloid-derived suppressor cells (MDSCs) for 3.5 months after sepsis induction." (PMID 29466409, 2018). "We first characterized PAXgene samples of 20 sepsis patients and ten healthy controls with respect to expression of the “immunosuppressive” miRNA signature and mRNA-levels of anti-inflammatory IL4, IL10, TGF-ß and pro-inflammatory “master cytokine” interleukin 1 beta (IL-1β)." (PMID 30332984, 2018). "We determined to find out if reductions in the plasma concentrations of the cytokines tumor necrosis factor (TNF)-α, IL-6, and IL-10, and the rate of change of IL-6 at 24 h after ICU admission were survival predictors for patients with sepsis and septic shock at an ICU in Ho Chi Minh City, Vietnam." (PMID 30400775, 2018). "Indeed, sepsis is associated with a monocyte hyporesponsiveness to LPS that appears to be proportional to the severity of sepsis and release of cytokines such as PGE2, TGF-β, and IL-10." (PMID 29924840, 2018). "We investigated if reduction in the serum concentration of the cytokines tumor necrosis factor α, interleukin (IL)-6 and IL-10, and the rate of change in the IL-6 level at 24 h after ICU admission were survival predictors for patients with sepsis and septic shock in a Vietnamese population." (PMID 30400775, 2018). "Sera collected on day four from patients with severe sepsis harbored significantly higher concentrations of TNF-α (5.7 vs. 0.7 pg/ml, P < 0.001), IL-6 (24.8 vs. 3.8 pg/ml, P < 0.001), and IL-10 (30.0 vs. 11.9 pg/ml, P = 0.040) than sera collected from healthy controls." (PMID 28086962, 2017). "For IL-10, the estimated means were also different between patients with sepsis and nonseptic patients (8.5 pg/mL and 1.9; P = 0.004)." (PMID 28769538, 2017). "In patients with septic AKI, the levels of TNF-α, IL-1β, IL-6, IL-2sR and IL-10 were significantly increased, while the levels of IL-8 was significantly decreased compared with sepsis patients without AKI." (PMID 28296904, 2017). "In addition, enhanced sepsis severity was also demonstrated by Scr (kidney injury), ALT (liver injury) and cytokines (TNF-α, IL-6 and IL-10) at 18h post-CLP." (PMID 28750040, 2017). "Therefore, we combined CLP-induced sepsis with intermittent blood sampling monitoring the endogenous production of IL-6, TNF-α and IL-10 in rats over 72 h." (PMID 29204105, 2017).
Sepsis (continued). "In contrast, IL-10-mediated control of excessive production of TNF-α and IL-6, which drive the pathological effects of the ‘cytokine storm’ found in patients with sepsis and septic shock may on the other hand be beneficial." (PMID 28216665, 2017). "Sepsis sera contained higher levels of TNF-α, IL-6, IL-10 and VEGF compared to controls." (PMID 28086962, 2017). "Thus, CD4+ DCs accumulate in the bone marrow during sepsis and modulate the cytokine secretion pattern of subsequently differentiating BMDC toward increased IL-10 production." (PMID 29218051, 2017). "In contrast, the production of IL-10 in the lungs of Il1rl1−/− and Stat6−/− mice was markedly reduced at day 15 after CLP, suggesting that type 2 cytokines and IL-33 are involved in the production of IL-10 in sepsis-surviving mice." (PMID 28374774, 2017). "For instance, LPS-stimulated PBMCs from survivors with severe sepsis produced more IL-12 and less IL-10 than those from nonsurvivors." (PMID 29221433, 2017). "High levels of IL-10 have been observed in patients who presented severe sepsis, mainly by gram-negative bacteria and, importantly, IL-10 has been previously associated with Bartonella infections." (PMID 28628613, 2017). "We investigated the effects of 24 h delayed normobaric oxygen (NBO2) and HBO2 treatment on the endogenous production of the inflammatory markers interleukin (IL)-6, tumor necrosis factor (TNF)-α and IL-10, and on mortality in rats with cecal ligation and puncture (CLP) induced sepsis." (PMID 29204105, 2017). "Furthermore, sepsis sera compared to healthy sera contained higher levels of TNF-α, IL-6, IL-10 and VEGF but a lower concentration of EGF." (PMID 28086962, 2017). "Anti-inflammatory cytokines such as IL-10, which possess antipyretic properties in humans and animals, have not been studied before in hypothermic patients with sepsis." (PMID 27737683, 2016). "The limitations placed on study power by multiple-association testing may in part account for our failure to replicate well-validated correlates of mortality in sepsis (in particular, TNF, IL-6, and IL-10)." (PMID 27170644, 2016). "Increased concentrations of both proinflammatory (e.g., tumor necrosis factor [TNF], interleukin-6 [IL-6], and IL-8) and anti-inflammatory (e.g., IL-1Ra, IL-10, and high IL-10/TNF ratios) cytokines in patients with sepsis have been previously demonstrated to predict mortality." (PMID 27170644, 2016). "The levels of the anti-inflammatory cytokines IL-4 and IL-10 as well as the components of innate immunity C-RP and SC5b-9 were high during sepsis in both gestational age groups, unlike the proinflammatory cytokines." (PMID 27293317, 2016). "Following CLP-induced sepsis, we detected a significant rise in the serum levels of proinflammatory cytokines such as IL-6 and TNF-α, as well as a simultaneous increase in the serum levels of the anti-inflammatory IL-10." (PMID 27044016, 2016). "Nevertheless, in sepsis with AKI, plasma NGAL and tumor necrosis factor alpha (TNFα) were already elevated at 6 hours without changes to serum creatinine and blood urea nitrogen, while IL-6 and IL-10 are increased only after 24 hours." (PMID 26880194, 2016). "Accumulated evidence has shown that a combination of Foxp-3, CTLA-4, TGF-βm+, and inhibitory cytokines (IL-10 and TGF-β) might serve as active markers for Tregs in the process of sepsis." (PMID 27835904, 2016). "IL-6 and IL-8 levels were found to be significantly higher in the serum of patients with severe sepsis compared to those without, while IL-10 was significantly lower in the EBC of patients with both severe sepsis and severe CAP, compared to those without." (PMID 28702287, 2016). "IL-10 serum concentrations in occurrence of sepsis showed no significant changes in comparison to bacteremia (28.12 ± 15.96 pg/ml)." (PMID 26315105, 2015).
Sepsis (continued). "However,TNF-α -238(AA), IL-1α-889(CC) and IL-10-1082(GG) genotypes appeared to be a higher producer by CBA assay, but IL-10 masked the expression of the high producing genotype of TNFα -238(AA) in sepsis patients." (PMID 26561011, 2015). "Increased values for IL-1β, IL-6, IL-10 and CXCL-2 were also observed in all volatile anesthetic sepsis groups compared to isoflurane-sham animals (all P <0.03), and IFN-γ was increased in isoflurane + CLP compared to isoflurane-sham animals (134.2 ± 131.9 versus 12.4 ± 12.2 pg/ml, P = 0.04)." (PMID 25887642, 2015). "Elevated levels of IL-1α, TNF-α and IL-10 were observed in patients with sepsis compared to healthy controls and non-sepsis patients." (PMID 26561011, 2015). "While higher blood IL10 levels paralleled the severity of septic shock, no clear differentiation was possible between SIRS and sepsis on the basis of IL10 alone." (PMID 26263001, 2015). "In yeast sepsis the cytokine IL-10 showed the best AUC values compared to Gram-negative sepsis and Gram-positive sepsis." (PMID 26635427, 2015). "Therefore, we investigated blood IL-1β, IL-6, IL-4, IL-5, IL-10 and IFN-γ, which play important roles in sepsis." (PMID 26586517, 2015). "High serum levels of CXCL10, IL-6, IL-10, TNF and IL-8 were reported in a canine sepsis model." (PMID 26222498, 2015). "This retrospective investigation analyzed the role of the cytokines IL1-β, sIL-2R, IL-6, IL-8, IL-10 and TNF-α as potential markers for major post-transplant adverse events including VOD, skin and intestinal GvHD, sepsis as well as bacterial, viral and fungal infections in 61 pediatric patients." (PMID 26315105, 2015). "The study of proinflammatory cytokines IL-6, TNF-α, IL-1β, and IL-8 and anti-inflammatory cytokines IL-10 and TGF-β as reliable biomarkers of neonatal infection has been shown to be potentially useful for early sepsis diagnosis and to predict the severity of disease at early stages of the infection." (PMID 25614712, 2014). "CAM decreases the ratio of serum IL-10 to serum TNF-α in patients with ventilator-associated pneumonia (VAP) and sepsis caused by gram-negative bacteria." (PMID 24632748, 2014). "During sepsis, atenolol did not alter the development of acute kidney injury or the levels of pro-inflammatory cytokines, but enhanced the release of IL-10." (PMID 25413250, 2014). "Thus, exogenous H2S reduced kidney injury from urinary-derived sepsis by decreasing the levels of NF-κB and TNF-α, and increasing the level of IL-10." (PMID 25009602, 2014). "The performances of IL-2, IL-6 and IL-10 to rule out the possibility of sepsis and intracranial infection are comparable with the role of CRP." (PMID 24887408, 2014). "Clinical and experimental studies have shown that LPS-induced sepsis can lead to a rapid simultaneous secretion of two functionally heterogeneous groups of cytokines: pro-inflammatory cytokines (e.g., TNF-α, IL-1β and IL-6) and anti-inflammatory (e.g., IL-10)." (PMID 24904237, 2014). "The area under ROC curve (AUC) of cytokines, such as IL-2, IL-6 and IL-10 were 0.901, 0.86, 0.888, respectively, which was employed to rule out the diseases of sepsis and intracranial infection." (PMID 24887408, 2014). "The AUCs for IL-2, IL-6, and IL-10 to rule out the possibility of sepsis and intracranial infection were bigger than CRP." (PMID 24887408, 2014). "Moreover, our experiments and other studies demonstrated that neutrophils were a major subset to produce IL-1β and IL-10 and highly expressed NOD2 during CLP-induced sepsis." (PMID 23675299, 2013). "Third, rIL-1β did not enhance serum and peritoneal C5a levels in Il-10−/− mice, which showed minimal C5a levels compared to WT mice with sepsis, whereas rIL-1β or rIL-10 administration to Nod2−/− mice enhanced serum and peritoneal C5a." (PMID 23675299, 2013). "The higher IL-10 levels observed in HIV-positive patients could explain their poorer response to acute infectious damage, with a worse sepsis outcome." (PMID 23374857, 2013).